PTCH1 (patched 1)
Diseases named in the same sentence as PTCH1 in open-access papers (continued):
Sharing a sentence is not in itself a finding about the gene and the disease.
Hirschsprung disease (2 papers, 2013 to 2020). Hirschsprung disease (HSCR) is a congenital intestinal motility disorder that is characterized by signs of intestinal obstruction due to the presence of an aganglionic segment of variable extent in the terminal part of the colon. "In a recent study, we have shown that genetic markers within GAL, GAP43 and NRSN1 contribute to the altered HSCR susceptibility, and importantly, the interaction networks among GAP43, NRSN1 and PTCH1 confer an increased risk to Hirschsprung disease." (PMID 32139661, 2020). "In conclusion, our results provide a first indication that common genetic variants within PTCH1 might confer altered risk to Hirschsprung disease in the Han Chinese population, further supporting PTCH1 as a potential susceptibility gene for HSCR." (PMID 24073265, 2013). "In the present study, we aimed to evaluate whether common variants in the PTCH1 gene might contribute to the altered risk of Hirschsprung disease in the Han Chinese population." (PMID 24073265, 2013). "In this study, we present the first indication that common genetic variants in the PTCH1 gene might confer altered susceptibility to Hirschsprung disease in the Han Chinese population and provide further support for the assumption that PTCH1 might be involved in the etiology of HSCR." (PMID 24073265, 2013). "Our results firstly suggest common variations of PTCH1 may be involved in the altered risk for HSCR in the Han Chinese population, providing potential molecular markers for early diagnosis of Hirschsprung disease." (PMID 24073265, 2013).
Hydrocephalus (2 papers, 2019 to 2021). Hydrocephalus is an active distension of the ventricular system of the brain resulting from inadequate passage of CSF from its point of production within the cerebral ventricles to its point of absorption into the systemic circulation. "Five genes (TRIM71, SMARCC1, PTEN, PIK3C, MTOR) were found to be involved in syndromic forms of hydrocephalus, and three other genes (FMN2, FOXJ1 and PTCH1) to be responsible for severe hydrocephalus with AS stenosis." (PMID 34092257, 2021).
influenza infection (2 papers, 2017 to 2023). "For example, SERPINB1 has been reported to influence the innate immune system during influenza infection, PTCH1 is important for macrophage chemotaxis during gastric inflammation, and PSAT1 regulates the inflammatory response in macrophages." (PMID 36761770, 2023). "Indeed, the Hh target gene Ptch1 was identified in an independent study as a critical host gene involved in influenza infection." (PMID 28837667, 2017).
ischaemic stroke (2 papers, 2019 to 2022). "Several variants detected in this study demonstrated suggestive association with outcome (p < 10−5), some of which are within or near genes with experimental evidence of influence on ischemic stroke volume and/or brain recovery (e.g., NTN4, TEK, and PTCH1)." (PMID 30796134, 2019).
laryngeal carcinoma (2 papers, 2022 to 2024). Carcinoma that arises from the laryngeal epithelium. "While LINC‐PINT expression was downregulated in laryngeal carcinoma tissues, it acted as a suppressor through the LINC-PINT/miR-425-5p/PTCH1 axis." (PMID 35568824, 2022).
lymph node metastasis (2 papers, 2019 to 2020). "The patients with PTCH1 mutations had a higher ratio of lung, liver, or distant lymph node metastasis and worse recurrence-free survival." (PMID 31704974, 2019). "Furthermore, the data demonstrated that Shh, Ptch1, Smo and Gli1 overexpression was markedly associated with a higher incidence of Lymph node metastasis and a more advanced TNM stage in GC (P<0.05)." (PMID 32328197, 2020). "In univariate analysis, the median overall survival (OS) was associated with histological differentiation, invasion depth, lymph node metastasis, TNM stage and the expression of Shh, Ptch1, Smo and Gli1 (P<0.05)." (PMID 32328197, 2020).
mesenchymal tumor (2 papers, 2016 to 2024). "This class of mesenchymal tumors comprises a wide array of molecular alterations, with the most common being GLI1::ACTB, GLI1::PTCH1 or GLI1::MALAT1." (PMID 39720383, 2024). "Given that the Hedgehog pathway has been shown to control the development of the mouse gut mesenchyme, we sought to determine whether two commonly studied murine models of the mesenchymal tumor GIST express key Hedgehog signaling components (Shh, Ihh, Ptch1, Smo, Gli1, Gli2, Gli3)." (PMID 27793025, 2016).
mesothelioma (2 papers, 2022 to 2025). A usually malignant and aggressive neoplasm of the mesothelium which is often associated with exposure to asbestos. "Based on our data, targeted treatments might also become a possible approach for mesothelioma, as alterations in hedgehog pathway-related genes (e.g., PTCH1/2 and SUFU) and hippo pathway-related genes (particularly NF2) were found." (PMID 36138075, 2022). "Suppressing Hedgehog signalling reduced cell viability in MPM cells, and treatment with vismodegib in a rat model of mesothelioma reduced the expression of target genes such as GLI1, HHIP and PTCH1." (PMID 36138075, 2022). "Here, we describe alterations in Hedgehog signalling genes PTCH1 (1.2%) and SUFU (0.8%) in the whole mesothelioma cohort." (PMID 36138075, 2022).
microcephaly (2 papers, 2016 to 2023). A congenital or acquired developmental disorder in which the circumference of the head is smaller than normal for the person's age and sex. "In human patients, gain-of-function mutations in Ptch1 gene, through partial or whole gene duplication, lead to microcephaly, a brain developmental defect characterized by small head size and the thinning of the cerebral cortex." (PMID 38201225, 2023). "Consistent with its role as a suppressor of Hh signaling, Ptch1 duplication in the human genome is associated with microcephaly and developmental delay." (PMID 38201225, 2023). "In summary, Ptch1 gain-of-function reduces Hh signaling in the developing cortex, decreases cortical size, and leads to developmental defects such as microcephaly." (PMID 38201225, 2023).
Nephroblastoma (2 papers, 2020). An embryonal neoplasm characterized by the presence of epithelial, mesenchymal, and blastema components. "Furthermore, Ptch1 gene mutations have been suggested to play an essential role in the pathogenesis of nephroblastoma." (PMID 33251198, 2020).
non-small cell lung carcinoma (2 papers, 2018 to 2022). A group of at least three distinct histological types of lung cancer, including non-small cell squamous cell carcinoma, adenocarcinoma, and large cell carcinoma. "PTCH1 is altered in 2.76% of non-small cell lung carcinoma patients with PTCH1 mutation present in 2.56% of all non-small cell lung carcinoma patients." (PMID 35982978, 2022).
oligodendroglioma (2 papers, 2023). A well-differentiated (WHO grade II), diffusely infiltrating neuroglial tumor, typically located in the cerebral hemispheres. "This further suggested that PTCH1 mutations may be responsible for the progression of oligodendroglioma into its more aggressive form." (PMID 37533228, 2023).
oral squamous cell carcinoma (2 papers, 2020 to 2023). "In the context of oral squamous cell carcinoma, disease severity has been positively correlated with the canonical activation of the Hedgehog pathway, occurring independently of PTCH1/SMO complex signaling." (PMID 32846867, 2020).
osteoarthritis (2 papers, 2015 to 2019). A noninflammatory degenerative joint disease occurring chiefly in older persons, characterized by degeneration of the articular cartilage, hypertrophy of bone at the margins and changes in the synovial membrane. "Ablation of Ptch1 led to increased chondrocyte proliferation and development of osteoarthritis and enchondroma." (PMID 31482846, 2019).
renal cell carcinoma (2 papers, 2023 to 2024). "In contrast, mRNA analysis of the elements of the Hedgehog signaling pathway, such as SHH, SMO, and GLI1 in tissue from renal cell carcinoma showed higher expression levels than healthy tissue, while an underexpression of PTCH1 was observed and specifically in patients older than 60 years." (PMID 38287479, 2024).
small bowel carcinoma (2 papers, 2010 to 2021).
spina bifida (2 papers, 2015 to 2022). A congenital neural tube defect in which vertebrae are not fully formed. "As in the exome dataset of proband SB1A with the EFNB1 variant (rs772228172), four variants were annotated as homozygous (CUBN, COMT, PTCH1 and TRDMT1) and eight variants as heterozygous (CUBN,MTRR, and VANGL1) in the reported spina bifida-related genes." (PMID 35741713, 2022).
teratoma (2 papers, 2020 to 2022). A non-seminomatous germ cell tumor characterized by the presence of various tissues which correspond to the different germinal layers (endoderm, mesoderm, and ectoderm). "The extensive expression of SHH protein in PTCH1+/− teratoma and presence of apoptotic cells in PTCH1−/− teratoma also support the idea that apoptosis both in PTCH1+/− and PTCH1−/− teratomas are induced by a PTCH1-independent manner." (PMID 35618979, 2022). "The PTCH1+/+ and PTCH1+/− teratomas were positive for all of these marker proteins." (PMID 35618979, 2022). "Since several groups have been reported that proapoptotic protein, BAX, expressed frequently in immature teratomas, BAX expression possibly accounts for the induction of apoptosis in PTCH1+/− and PTCH1−/− teratomas." (PMID 35618979, 2022). "Apoptotic cells were found in PTCH1+/− and in PTCH1−/− teratomas, but there was no statistical difference of the apoptotic rate between two genotypes, suggesting the apoptosis in these teratoma was induced by ligand-free PTCH1-independent fashion." (PMID 35618979, 2022). "On the other hand, PTCH1−/− teratomas frequently lacked mesodermal and/or endodermal components." (PMID 35618979, 2022).
thyroid cancer (2 papers, 2022). "Patched-1 (PTCH1) receptor, which activated by binding SHH, marginally expressed all thyroid cancer cell lines, especially more expressed in BHT101 and CAL62 cells." (PMID 35406554, 2022).
trichoblastoma (2 papers, 2015 to 2024). A benign hair follicle neoplasm with trichoblastic differentiation. "A role for alterations of the oncosuppressor gene PTCH1 on chromosome 9q22.3 in promoting BSS was hypothesized by early studies that detected pathogenic variations of this gene in patients affected by trichoblastomas and trichoepitheliomas; however, subsequent works did not confirm this finding." (PMID 38673513, 2024).
urothelial carcinoma (2 papers, 2022 to 2023). A malignant neoplasm derived from the transitional epithelium of the urinary tract (urinary bladder, ureter, urethra, or renal pelvis). "As per findings of a few studies, dysregulation of SHH ligand or one of its downstream mediators, for instance, PTCH1, SMO, or GLI1, has been linked to urothelial carcinoma initiation and progression and in modulating cancer stem cell activities." (PMID 37069207, 2023).
-facial clefting (1 paper, 2009). "Oro-facial clefting is a recognized feature of NBCCS, occurring with a significantly increased incidence to that found in the general population, whilst mutations in PTCH1 have also been associated with isolated cleft lip and palate." (PMID 19394325, 2009).
acute pancreatitis (1 paper, 2012). An acute inflammatory process that leads to necrosis of the pancreatic parenchyma. "Specially, the mRNA level of Gli1 and Ptch1 all augmented as high as 20 folds compared with PBS control, which indicated that the initiation and upregulation of autocrine Shh signaling loop during the progression of acute pancreatitis in mice was established in our study." (PMID 22956998, 2012).
adenomyosis (1 paper, 2025). The growth of endometrial tissue inside the muscular wall of the uterine corpus. "IHH, as well as its transcription factor, receptor, and target gene (SOX17, PTCH1, and HHIP, respectively), exhibiting spatial expression characteristics, were highly expressed in the invaginating site of adenomyosis." (PMID 40190183, 2025).
adenovirus infection (1 paper, 2020). "(D) Expression of Gli1 and Ptch1 in Dyrk2-/- MEFs overexpressing human DYRK2 or DYRK2-K251R (kinase dead) constructs via adenovirus infection was measured by qPCR." (PMID 32758357, 2020).
allergic asthma (1 paper, 2022). A asthma with a basis in a pathological type I hypersensitivity reaction. "The goal of this study was to investigate the biological role of PTCH1, SMO and GLI in airway epithelial cell models using various gain and loss of function assays and pharmacologic inhibition, and in a house dust mite model of allergic asthma using mice haplodeficient in Ptch1 (Ptch1+/−)." (PMID 36230980, 2022).
alopecia (1 paper, 2025). Hair loss usually from the scalp. "PTCH1 mutations or dysfunction can impair SHH signaling, resulting in feather follicle miniaturization, feather cycle disruption, and contributing to alopecia." (PMID 40872583, 2025).
atrial fibrillation (1 paper, 2022). A disorder characterized by an electrocardiographic finding of a supraventricular arrhythmia characterized by the replacement of consistent P waves by rapid oscillations or fibrillatory waves that vary in size, shape and timing and are accompanied by an irregular ventricular response. "The variant in ATP2B1 gene (rs2681492) was associated with CAD and rs2810915 variant in PTCH1 gene was significantly associated with atrial fibrillation." (PMID 36407428, 2022).
autism (1 paper, 2023). Persistent deficits in social interaction and communication and interaction as well as a markedly restricted repertoire of activity and interest as well as repetitive patterns of behavior. "Considering the role of PTCH1 in embryonic development and neuronal activity, it is not unlikely that the PTCH1 mutation plays a role in the etiology of autism and should be considered in autistic patients." (PMID 37752108, 2023).
Axenfeld-Rieger syndrome (1 paper, 2021). Axenfeld-Rieger syndrome (ARS) is a generic term used to designate overlapping genetic disorders, in which the major physical condition is anterior segment dysgenesis of the eye. "A frameshift variant and multiple missense variants in PTCH1 have previously been reported in multiple cases with isolated and syndromic ocular developmental anomalies, including C/M, Peters anomaly, and Axenfeld-Rieger syndrome." (PMID 33418956, 2021).
Bardet-Biedl syndrome (1 paper, 2020). A ciliopathy with multisystem involvement. "Patched 1, GPR161, SMO and other ciliary membrane proteins are all ferried out of cilia in a regulated manner by an evolutionarily conserved complex of eight Bardet-Biedl Syndrome (BBS) proteins, the BBSome." (PMID 32510327, 2020).
Barrett esophagus (1 paper, 2013). Esophageal lesion lined with columnar metaplastic epithelium which is flat or villiform. "In Barrett’s esophagus, an early precursor of esophageal adenocarcinomas, the expression of Shh and Ihh is increased in the epithelium, which is associated with stromal expression of the Hh target genes PTCH1 and BMP4." (PMID 23303278, 2013).
bone tumor (1 paper, 2019). "Ptch1 deficiency-induced cartilage/bone tumors were originated from Prrx1 lineage cells." (PMID 31482846, 2019). "In addition, Ptch1 deletion in MSCs causes much severe joint deformation and exostoses and only Ptch1 deletion in MSCs induces cartilage/bone tumor formation." (PMID 31482846, 2019). "Treating the mice that had mesenchymal cells lacking Ptch1 with a drug that inhibits Wnt signaling reduced the growth of cartilage and bone tumors." (PMID 31482846, 2019).
brachydactyly (1 paper, 2021). A disease characterized by the presence of brachydactyly, including syndromic and non-syndromic forms. "Of the genes associated with congenital abnormality, four genes (HDAC4, PTCH1, EHMT1, SYK) were associated with brachydactyly, according to the DisGeNET database." (PMID 34246298, 2021). "Additionally, PTCH1 has also been previously involved in brachydactyly as part of Hh signaling." (PMID 34246298, 2021).
brachydactyly type A1 (1 paper, 2025). A rare, congenital limb malformation characterized by shortened or underdeveloped middle phalanges of all digits, that are sometimes fused with the terminal phalanges. "PTCH1 has also been found to be a negative regulator of Indian hedgehog (IHH) signaling in a mouse model of Brachydactyly type A1, a cause of short stature, with impaired interaction between IHH and receptor PTCH1 contributing to the phenotype." (PMID 40577202, 2025).
cartilage tumors (1 paper, 2019). "Wnt/β-Catenin signaling was activated in Ptch1-/- MSCs and human bone/cartilage tumors." (PMID 31482846, 2019).
cerebral infarction (1 paper, 2022). An ischemic condition of the brain, producing a persistent focal neurological deficit in the area of distribution of the cerebral arteries. "This case report presents a novel case of epidermal nevus syndrome with a missense mutation in PTCH1 gene and cerebral infarction." (PMID 36171624, 2022). "However, in addition to the typical clinical characteristics, the patient also has a mutation (c.109G > T) in PTCH1 gene and cerebral infarction." (PMID 36171624, 2022). "This case report may contribute to characterizing the phenotype of epidermal nevus syndrome, help clinicians be aware of the association of this condition with PTCH1 gene and cerebral infarction, raise clinical suspicion, and improve early therapy." (PMID 36171624, 2022). "Epidermal nevus syndrome is a rare syndrome, and epidermal nevus syndrome with the mutation of PTCH1 gene and cerebral infarction is even rarer and has not been reported to the best of our knowledge." (PMID 36171624, 2022).
cholangiocarcinoma (1 paper, 2021). A carcinoma that arises from the intrahepatic biliary tree (intrahepatic cholangiocarcinoma) or from the junction, or adjacent to the junction, of the right and left hepatic ducts (hilar cholangiocarcinoma). "Both mutation and copy number alterations (CNA) affecting Hedgehog pathway main members, namely GLI1, GLI2, GLI3, SMO, PTCH1/2, SUFU, and DHH, have been observed in mixed cholangiocarcinoma patients with different frequencies." (PMID 34638259, 2021).
chronic bronchitis (1 paper, 2019). A type of chronic obstructive pulmonary disease characterized by chronic inflammation in the bronchial tree that results in edema, mucus production, obstruction, and reduced airflow to and from the lung alveoli. "PTCH1 provides a novel target to reduce chronic bronchitis in COPD patients." (PMID 30833624, 2019). "Taken together, these results suggest that up-regulation of PTCH1 in the COPD airway may contribute to mucous hypersecretion and the “chronic bronchitis” phenotype of COPD patients." (PMID 30833624, 2019).
chronic myeloid leukemia (1 paper, 2017). "Patched homolog 1 gene (PTCH1) expression and the ratio of PTCH1 to Smoothened (SMO) expression have been proposed as prognostic markers of the response of chronic myeloid leukemia (CML) patients to imatinib." (PMID 28704552, 2017).
chronic obstructive pulmonary disease (1 paper, 2019). A chronic and progressive lung disorder characterized by the loss of elasticity of the bronchial tree and the air sacs, destruction of the air sacs wall, thickening of the bronchial wall, and mucous accumulation in the bronchial tree. "Genome-wide association studies have linked gene variants of the receptor patched homolog 1 (PTCH1) with chronic obstructive pulmonary disease (COPD)." (PMID 30833624, 2019).